MEN1 (menin 1)
Diseases named in the same sentence as MEN1 in open-access papers (continued):
Sharing a sentence is not in itself a finding about the gene and the disease.
primary hyperparathyroidism (81 papers, 2010 to 2026). Hyperfunction of the parathyroid glands resulting in the overproduction of parathyroid hormone. "Some MEN1 genotypes are associated with an earlier age at primary hyperparathyroidism diagnosis and a shorter time to recurrence." (PMID 38928056, 2024). "The algorithm-based treatment for MEN1-associated primary hyperparathyroidism is surgical removal, though this becomes more complex when the parathyroid gland is ectopic." (PMID 39459453, 2024). "In this respect, multiple parathyroid tumors causing primary hyperparathyroidism are the most common manifestation of MEN1, with more than 90% penetrance by age 40–50." (PMID 38294658, 2024). "Our sample-focused analysis followed a triad of turning points between the pancreas and parathyroid with the confirmation of primary hyperparathyroidism: hypercalcemia-linked pancreatitis, MEN1 gene pathogenic variants, and insulin resistance." (PMID 38928056, 2024). "Most of MEN1 patients suffer from primary hyperparathyroidism (PHPT) caused by parathyroid hyperplasia and/or adenoma." (PMID 37795364, 2023). "The R52G mutation was first identified in a MEN1 patient who developed primary hyperparathyroidism and a PanNET." (PMID 35941657, 2022). "The diagnosis of primary hyperparathyroidism under the age of 40 years prompted genetic testing for hereditary causes of hypercalcemia, including MEN1, MEN4, and hyperparathyroidism jaw tumor syndrome." (PMID 35323929, 2022). "Here, we report a heterozygous c.1138C>T (p.Leu380Phe) CDC73 germline variant in a clinically diagnosed MEN1 patient, based on combined occurrence of primary hyperparathyroidism, acromegaly, and a PNEN." (PMID 33150274, 2020). "Considering the higher risk of reoperation in patients with MEN1 than in patients with sporadic primary hyperparathyroidism, limited exploration has the benefit of facilitating future surgery via preservation of an unresected area." (PMID 32606444, 2020). "Patients with MEN1 typically present with primary hyperparathyroidism caused by multiple parathyroid tumors, however, thymic and bronchial carcinoid tumors are also less common manifestations." (PMID 31727021, 2019). "This is in accordance with the clinical presentation of MEN1, which is associated with an estimated penetrance of primary hyperparathyroidism of 90%." (PMID 30990521, 2019). "Most commonly, patients with MEN1 manifest primarily with signs and symptoms linked to primary hyperparathyroidism." (PMID 30459713, 2018). "Bronchial/thymic NET has been reported as the presenting feature of MEN1 in one series; however all patients had concurrent primary hyperparathyroidism and several had other MEN1 associated tumours." (PMID 28965289, 2017). "Primary hyperparathyroidism (PHPT) is the most prevalent clinical expression in MEN-1 mutation carriers, present in more than 90% of cases." (PMID 21318141, 2010). "MEN1 is an autosomal dominant familial cancer predisposition syndrome whose most prominent expressions include multiglandular primary hyperparathyroidism, anterior pituitary tumors, foregut carcinoid tumors, and tumors of gastroenteropancreatic neuroendocrine cells." (PMID 37409236, 2023). "After excision of a large, invasive, thymic NET, the patient experienced an initial period of remission, but CS recurred after 2 years, this time associated with primary hyperparathyroidism and hyperprolactinemia, and a clinical and genetic diagnosis of MEN1 was confirmed." (PMID 37409236, 2023). "Likewise, FIHP is characterized by the onset of primary hyperparathyroidism alone and is related to specific mutations of MEN1 gene that often include missense mutations and only occasionally nonsense or frameshift mutations." (PMID 33312161, 2020).
primary hyperparathyroidism (continued). "Diagnostic criteria for MEN1 include the presence of at least two of the three main MEN1 associated lesions (primary hyperparathyroidism, GEP NET and anterior pituitary tumors) or the association of any typical MEN1-associated neoplasia and a positive familial history." (PMID 24961548, 2014). "There are several hereditary forms of primary hyperparathyroidism (pHPT), including MEN1, MEN2A, MEN4, and hyperparathyroidism-jaw tumor syndrome (HPT-JT), in which imaging often proves non-contributory." (PMID 40807089, 2025). "Other MEN1 phenotype specifications in this focused-analysis included with regard to primary hyperparathyroidism a pancreatic complication (acute and chronic pancreatitis) in a 56-year-old male) but also a normocalcemic variant." (PMID 38928056, 2024). "Based on her medical history and examination, the diagnosis of primary hyperparathyroidism in MEN1 was made, and she underwent total parathyroidectomy with autotransplantation with SPY-Elite®️ Fluorescence Imaging (Stryker Corp., Kalamazoo, MI)." (PMID 38586714, 2024). "Primary hyperparathyroidism in MEN1 (MEN1-PHPT) is distinguished by early onset and clinical aggressiveness." (PMID 39519139, 2024). "The estimated MEN1 prevalence is two to three cases per 100,000 people with primary hyperparathyroidism being reported in 85–90% of subjects." (PMID 38928056, 2024). "Duodeno-pancreatic and thymus MEN1-NETs represent the second most common neoplasia following the presence of parathyroid NETs, meaning that many individuals confirmed with a pancreatic MEN1-NET have already been identified with primary hyperparathyroidism." (PMID 38928056, 2024). "Primary hyperparathyroidism is the most characteristic finding in MEN1, and intraoperative identification and accurate removal of the diseased parathyroid glands are vital since incomplete excision results in recurrence." (PMID 38586714, 2024). "In MEN4, primary hyperparathyroidism has been reported in up to 80–90% of cases and presents at an older age as compared to MEN1, with a female predominance." (PMID 37761922, 2023). "I also hope that doctors can carry out similar research to find a treatment method with less trauma and better efficacy for patients with MEN1 complicated with primary hyperparathyroidism." (PMID 37795364, 2023). "The MEN1 patient’s case was complicated with relapsed primary hyperparathyroidism (PHPT), and they received ultrasound-guided radiofrequency ablation (RFA)." (PMID 36292242, 2022). "MEN1 is mainly characterized by primary hyperparathyroidism, pituitary adenomas, and neuroendocrine tumors (NETs) and is caused by a mutation in menin." (PMID 35355569, 2022). "Primary hyperparathyroidism in the context of MEN1 involves a multiglandular disease with small hyperplastic glands rather than adenomas, which remains challenging for most imaging modalities and surgery techniques." (PMID 35407574, 2022). "The family members had been tested for MEN1 biochemically before this study, and the mother was diagnosed with a primary hyperparathyroidism and underwent surgery at the age of 47." (PMID 34711244, 2021). "The three most prevalent lesions typical of MEN1 in our series were 71 primary hyperparathyroidism (PHPT) (93.42%), 50 gastro-entero-pancreatic neuroendocrine tumors (GEP-NETs) (65.78%), and 48 pituitary tumors (63.15%)." (PMID 33407684, 2021). "MEN1 primary hyperparathyroidism is now well established owing to its role in benign parathyroid lesions or PA." (PMID 33778063, 2021). "Based on these findings, we diagnosed this subject with MEN1 accompanied by pituitary neoplasia, primary hyperparathyroidism, a giant cervical lipoma and multiple abnormal fatty deposits in the pancreas." (PMID 34384417, 2021). "The earliest and most common MEN1-related feature is primary hyperparathyroidism due to parathyroid hyperplasia or parathyroid adenoma." (PMID 33807230, 2021).
primary hyperparathyroidism (continued). "Based on known cases, guidelines advocate that screening for primary hyperparathyroidism in patients with MEN1 is initiated at the age of 8 years." (PMID 30990521, 2019). "By age 50, it is estimated that 100% of patients with MEN1 will have been diagnosed with primary hyperparathyroidism." (PMID 30459713, 2018). "Traditionally, reoperation is considered a failure, but in the case of MEN1-related primary hyperparathyroidism, we recommend redefining goals and expectations." (PMID 27402205, 2016). "We performed a retrospective cohort study at a high-volume tertiary medical center including patients with MEN1 and primary hyperparathyroidism, who underwent STP or unilateral clearance as their initial surgery from 1995 to 2015." (PMID 27402205, 2016). "In this study, we found that unilateral clearance can be performed in a subgroup of MEN1 patients with primary hyperparathyroidism who have concordant preoperative sestamibi and ultrasound localization studies." (PMID 27402205, 2016). "Parathyroid tumors, resulting in primary hyperparathyroidism, are the most common feature of MEN1 and occur in ∼95% of MEN1 patients." (PMID 23933118, 2014). "Hondaet al.3 reported PA associated with primary hyperparathyroidism and breast cancer and a LOH of the MEN1 locus in the parathyroid adenoma and in the breast cancer tissue." (PMID 25210615, 2014). "Although the defective MEN-1 gene is a tumour suppressor, the parathyroid carcinoma is diagnosed in the smaller proportion of patients than in sporadic primary hyperparathyroidism." (PMID 21318141, 2010). "To date, fewer than 100 cases of MEN4 have been reported in the literature; the typical clinical manifestations are similar to MEN1, including primary hyperparathyroidism, pituitary adenomas, and neuroendocrine tumors; however, they typically present in a milder form and at an older age." (PMID 39519139, 2024). "One patient (MEN1 c.526G > T) associated PHEO and familial hypocalciuric hypercalcemia, and 2 other had PHEO and idiopathic hypercalcemia (RB2 c.644C > T), respectively, primary hyperparathyroidism (ATM c.5639C > T)." (PMID 39673085, 2024). "Herein, we would like to advocate that the use of parathyroid gland autofluorescence with real-time intrinsic NIR imaging may be useful for identifying parathyroid tumors in patients with primary hyperparathyroidism in MEN1." (PMID 38586714, 2024). "Recently, a new concept has been released, namely, familial isolated pancreatic NETs (FIPNET), that includes subjects carrying MEN1 pathogenic variants and a single clinical manifestation at the level of the pancreas with normal calcium/PTH levels (primary hyperparathyroidism-free phenotype)." (PMID 38928056, 2024). "Moreover, a study from 2024 assessed the recurrence after initial parathyroidectomy in 517 MEN1-positive subjects confirmed with primary hyperparathyroidism (between 1990 and 2019)." (PMID 38928056, 2024). "Of note, as opposite to MEN1, most cases of primary hyperparathyroidism were caused by a single-gland condition, not a multi-gland disease." (PMID 38928056, 2024). "The prominent expressions of MEN1 include primary hyperparathyroidism, tumors of the anterior pituitary, gastroenteropancreatic neuroendocrine tumors, and bronchial carcinoid tumors along with several common non-endocrine manifestations such as cutaneous angiofibromas and leiomyomas." (PMID 37409236, 2023). "In fact, 90% of patients with MEN1 develop primary hyperparathyroidism before the age of 50." (PMID 36950054, 2023). "According to case reports in the literature, the youngest age of onset is 15 years in MEN4, while in MEN1, primary hyperparathyroidism might occur at a much earlier age (as young as 5 years)." (PMID 35355569, 2022).
primary hyperparathyroidism (continued). "One previous case report of the sporadic MEN1 case mutated with c.1546dupC in a 20-year-old female presenting with Cushing disease and primary hyperparathyroidism showed the possibility of early development of MEN1-related tumors in the affected individuals with the c.1546dupC mutation." (PMID 34160414, 2021). "As MEN1 was initially ruled out, another genetic cause of primary hyperparathyroidism and hypercalcemia was identified." (PMID 34889280, 2021). "Primary hyperparathyroidism affects the majority of MEN1 individuals by age 50 years." (PMID 28736585, 2017). "Zollinger-Ellison syndrome may be the presenting feature of MEN1 in up to a third of patients, however the majority of these patients will have biochemical evidence of primary hyperparathyroidism at the time of presentation." (PMID 28965289, 2017). "Some MEN1 patients with primary hyperparathyroidism who have concordant localizing studies may be selected for unilateral clearance as an alternative to STP." (PMID 27402205, 2016). "Primary hyperparathyroidism was predominantly diagnosed before MEN1 was diagnosed." (PMID 27842554, 2016). "Interestingly, the diagnosis of primary hyperparathyroidism in MEN4 appears to occur later than MEN1 and predominantly in women with the average age reported being 56 years compared to 20–25 years for MEN1." (PMID 26257968, 2015). "Routine testing for MEN-1 mutation in young patients with primary hyperparathyroidism is not recommended, as these mutations are rare in unselected patients even below 40 years of age." (PMID 21318141, 2010). "As the patient’s father passed away due to complications of peptic ulcers and hailed from a region with high rates of MEN1, PTH and calcium levels were checked, confirming the diagnosis of primary hyperparathyroidism (pHPT)." (PMID 40476723, 2025). "Parathyroid tumors, resulting in primary hyperparathyroidism (PHPT), affect up to 95% of MEN1 patients and represent the first manifestation of the syndrome, with more than 85% of cases between ages 20 and 25 years." (PMID 33312161, 2020). "Primary hyperparathyroidism (PHPT) is the most common feature of MEN1 and presents in approximately 90% of MEN1 patients." (PMID 26640724, 2015). "We performed a descriptive case–control study in which the different outcomes for sporadic, MEN1- and MEN2A-related primary hyperparathyroidism were assessed and possible contributing confounding factors were analyzed." (PMID 23547958, 2013). "Contrastingly, actionable non-cancer symptoms such as primary hyperparathyroidism for MEN1 were included in the surveillance table." (PMID 40183848, 2025). "The absence of p27 protein expression has been described in primary hyperparathyroidism and MEN1 mutant parathyroids." (PMID 38244045, 2024). "Primary hyperparathyroidism results in MEN4, as in MEN1, the most frequent endocrine neoplasm." (PMID 35355569, 2022). "We present a case of late-onset MEN1 in the absence of the most common feature, primary hyperparathyroidism, but with the presence of a pNET and cutaneous findings." (PMID 28736585, 2017). "Primary hyperparathyroidism must be ruled out, because this is present in 90% of MEN1 patients." (PMID 26124750, 2015). "Although investigations for primary hyperparathyroidism were negative in our case, the patient showed two endocrine tumors over several years, which could be related to the presence of MEN1." (PMID 25210615, 2014).
hyperparathyroidism (74 papers, 2008 to 2025). "While MEN1, MEN4, and hyperparathyroidism-jaw tumor syndrome involve inactivating pathogenic variants of tumor suppressor genes MEN1, CDKN1B, and CDC73, respectively, MEN2 is caused by activating mutations of RET proto-oncogene." (PMID 40277809, 2025). "The patient's hyperparathyroidism and associated clinical features represent the most common and earliest manifestation of MEN1." (PMID 41541958, 2025). "She underwent parathyroidectomy (with right forearm re-implantation) and right hemithyroidectomy to address the hyperparathyroidism that was caused by MEN1." (PMID 40144450, 2025). "In the literature, there are several reports of MEN1 alterations related only to isolated hyperparathyroidism, while the same variant in other families results in different phenotypes with other MEN1-associated tumors." (PMID 33807230, 2021). "Hyperparathyroidism associated with MEN1 is more aggressive (e.g., a greater decline in bone mineral density as well as urolithiasis at a young age)." (PMID 33807230, 2021). "Our results support the benign nature of this CDC73 variant, as individuals with both alterations presented a prevalence of hyperparathyroidism of 50% (3/6), similar to the 55% (6/11) of family members with only the MEN1 mutation." (PMID 34889280, 2021). "It is also rarely associated with Cushing’s Disease; the coexistence of hyperparathyroidism and hypercortisolism is associated with both MEN1 and MEN2." (PMID 28965289, 2017). "MEN1-associated hyperparathyroidism patients present earlier than sporadic patients but with similar symptoms." (PMID 21747852, 2011). "Familial hyperparathyroidism associated with MEN1 and MEN2A and familial isolated hyperparathyroidism are also managed surgically." (PMID 21747852, 2011). "All were commenced on cinacalcet 30 mg bd for MEN1 associated hyperparathyroidism; doses were subsequently reduced to 30 mg od in four patients." (PMID 20585352, 2010). "It is recommended that biochemical screening for hyperparathyroidism, as well as for the other tumours, should be performed every 1–3 years in the carriers of MEN-1 mutation." (PMID 21318141, 2010). "Genes associated with hyperparathyroidism include MEN1, MEN2A, CDC73, CCND1, RET, CASR, and CDKN1B." (PMID 40149408, 2025). "For example, in patients with hyperparathyroidism associated with MEN1, even after the removal of three and a half or more parathyroid glands, 5% to 6% of patients may continue to have the disease." (PMID 40224187, 2025). "Testing for MEN1 germline mutations might also be advised for people exhibiting atypical MEN1 symptoms, like multiglandular hyperparathyroidism." (PMID 39194755, 2024). "A similar observation of the two-hit hypothesis holds true for inherited causes of hyperparathyroidism due to tumor suppressor genes such as MEN1 and CDKN1B." (PMID 33716975, 2021). "To date, reports have shown that more than 10% of patients with hyperparathyroidism may have a germline mutation involving the MEN1, RET, cell division cycle 73 (CDC73), calcium-sensing receptor (CASR), cyclin-dependent kinase inhibitor (CDNK1B), or PTH genes." (PMID 29983117, 2018).